SLC22A7 (solute carrier family 22 member 7)
Description:
[Isoform 2]: Functions as a Na(+)-independent bidirectional multispecific transporter. Contributes to the renal and hepatic elimination of endogenous organic compounds from the systemic circulation into the urine and bile, respectively. Capable of transporting a wide range of purine and pyrimidine nucleobases, nucleosides and nucleotides, with cGMP, 2'deoxyguanosine and GMP being the preferred substrates. Functions as a pH- and chloride-independent cGMP bidirectional facilitative transporter that can regulate both intracellular and extracellular levels of cGMP and may be involved in cGMP signaling pathways. Mediates orotate/glutamate bidirectional exchange and most likely display a physiological role in hepatic release of glutamate into the blood. Involved in renal secretion and possible reabsorption of creatinine. Able to uptake prostaglandin E2 (PGE2) and may contribute to PGE2 renal excretion (Probable). Also transports alpha-ketoglutarate and urate. Apart from the orotate/glutamate exchange, the counterions for the uptake of other SLC22A7/OAT2 substrates remain to be identified. [Isoform 1]: Non functional transporter. [Isoform 3]: Involved in the uptake of prostaglandin F2-alpha (PGF2-alpha).
Synonyms: NLT; OAT2; hOAT11
Tractability: Small molecule: it belongs to a druggable protein family. Antibody: UniProt places it where antibodies can reach, with high confidence; its Gene Ontology location is reachable by antibodies, with high confidence; UniProt predicts a signal peptide or a membrane-spanning region.
Target class: SLC superfamily of solute carriers; Electrochemical transporter; SLC22 family of organic cation and anion transporters; Transporter
Safety:
Unwanted effects reported when the protein is acted on. In parentheses: how it was acted on, where the effect was seen, and who reports it.
diarrhea (source: ClinPGx)
drug toxicity (source: ClinPGx)
Gene: Protein-coding gene on chromosome 6 (43,295,694 to 43,305,543, forward strand). Ensembl gene ENSG00000137204.
Subcellular location: Basolateral cell membrane (Isoform 2); Apical cell membrane; Cell membrane; Cytoplasm, cytosol (Isoform 1)
Pathways (Reactome):
Drug ADME: Aspirin ADME
Transport of small molecules: Organic anion transport by SLC22 transporters
Gene Ontology:
Molecular function: alpha-ketoglutarate transmembrane transporter activity; prostaglandin transmembrane transporter activity; protein binding; transmembrane transporter activity; secondary active transmembrane transporter activity
Biological process: alpha-ketoglutarate transport; prostaglandin transport; transmembrane transport; xenobiotic metabolic process; sodium-independent organic anion transport
Cellular component: apical plasma membrane; basal plasma membrane; basolateral plasma membrane; plasma membrane; membrane; cytosol
Genetic constraint (gnomAD): Loss-of-function variants: 46 observed, 59.46 expected, observed/expected ratio (o/e) 0.77, 90% interval 0.61 to 0.99. The upper end of that interval is the gene's LOEUF score, 0.99, which puts it in group 4 of 6, group 1 being the genes least tolerant of losing a copy. Missense variants: 581 observed, 711.05 expected, observed/expected ratio (o/e) 0.82, 90% interval 0.76 to 0.88. Synonymous variants: 276 observed, 317.12 expected, observed/expected ratio (o/e) 0.87, 90% interval 0.79 to 0.96.
Homologues: Orthologues: chimpanzee SLC22A7 (99% identical), macaque SLC22A7 (97% identical), pig SLC22A7 (90% identical), rabbit SLC22A7 (87% identical), rat Slc22a7 (78% identical), mouse Slc22a7 (76% identical), guinea pig SLC22A7 (76% identical), zebrafish slc22a7b.1 (45% identical), zebrafish zmp:0000001102 (41% identical), zebrafish slc22a7b.3 (41% identical), zebrafish slc22a7b.2 (36% identical), Caenorhabditis elegans oct-1 (30% identical), and 40 more. Paralogues in human: SLC22A12 (35% identical), SLC22A6 (35% identical), SLC22A8 (35% identical), SLC22A11 (33% identical), SLC22A13 (33% identical), SLC22A24 (32% identical), SLC22A25 (30% identical), SLC22A9 (30% identical), SLC22A10 (30% identical), SLC22A5 (30% identical), SLC22A1 (29% identical), SLC22A15 (29% identical), and 10 more.
Diseases named in the same sentence as SLC22A7 in open-access papers:
SLC22A7 is named in the same sentence as 32 diseases in open-access papers, as found by Europe PMC text mining. Sharing a sentence is not in itself a finding about the gene and the disease. The quoted sentences say what the papers report.
hepatocellular carcinoma (5 papers, 2016 to 2024). A malignant tumor that arises from hepatocytes. "Database analysis has also shown that SLC22A7 expression is associated with multicentric tumor occurence in hepatocellular carcinoma." (PMID 29703252, 2018). "In hepatoma, HepaRG cells and human hepatocytes, the SLCO1B1, SLCO2B1, SLC22A1 and SLC22A7 expression was down-regulated by an RAR agonist, all-trans retinoic acid." (PMID 36839686, 2023).
diabetes mellitus type 2 (3 papers, 2018 to 2024). "Our results suggest that genetic variation in or near TAF3, MUC1/TRIM46, SHROOM3, and SLC22A7 are associated with the regulation of serum Mg2+ concentrations which may be partially explained by renal function, in type 2 diabetes." (PMID 38279093, 2024). "In conclusion, serum magnesium concentrations are associated with genetic variability around the regions of TAF3, MUC1/TRIM46, SHROOM3, and SLC22A7 in type 2 diabetes." (PMID 38279093, 2024).
cardiomyopathy (2 papers, 2022 to 2025). A disease of the heart muscle or myocardium proper. "Variants SLC22A17-rs4982753 and SLC22A7-rs4149178 were associated with decreasing risk of cardiomyopathy in Canadian CCS (p = 0.0078 and 0.0034, respectively) and were validated in a replication cohort (p = 0.0071 and 0.047, respectively)." (PMID 40413218, 2025). "Different variants in the Solute carrier (SLC) transporters: SLC28A3, SLC22A17, SLC22A7, and SLC22A6 were identified as associated with cardiomyopathy in CCS." (PMID 40413218, 2025). "Most research was done on doxorubicin-induced cardiomyopathy and for seven genetic variants in CELF4, GPR35, HAS3, RARG, SLC22A17, SLC22A7 and SLC28A3, replication studies were performed without consistent results." (PMID 36536332, 2022).
high blood pressure (2 papers, 2015 to 2023). "In females, six loci (P < 5 × 10−8) were shared between testosterone and high blood pressure, and 3 (CYP11B1, SLC16A1, SLC22A7) of them were in DMET gene regions." (PMID 36635277, 2023).
leukemia (2 papers, 2023 to 2024). A malignant (clonal) hematologic disorder, involving hematopoietic stem cells and characterized by the presence of primitive or atypical myeloid or lymphoid cells in the bone marrow and the blood. "However, a study in 344 pediatric cancer patients (mostly with leukemias and lymphomas) of mixed ethnicity (Canada) described an association between the G allele of the SLC22A7 rs4149178 SNP and a lower risk of cardiotoxicity during anthracycline treatment." (PMID 36980706, 2023). "Methotrexate, used in the treatment of several cancers (uterus, breast, and lung carcinomas, certain cancers of the head and neck, and some lymphomas and leukemias), has been described as a substrate of OAT1 (SLC22A6) and OAT2 (SLC22A7)." (PMID 39143954, 2024).
liver cancer (2 papers, 2020 to 2022). An epithelial or non-epithelial malignant neoplasm that arises from the liver. "As the hepatocyte-specific markers were abundantly expressed in highly differentiated liver cancer cells, the close association between SLC22A7 and hepatocyte-specific markers suggested that SLC22A7 might participate in tumor differentiation." (PMID 35707353, 2022). "Out of the classical OATs only OAT2 (SLC22A7) has a favorable prognostic value in renal and liver cancer." (PMID 32599841, 2020).
osteosarcoma (2 papers, 2018 to 2022). A usually aggressive malignant bone-forming mesenchymal neoplasm, predominantly affecting adolescents and young adults. "SLC22A7 (Solute Carrier Family 22 Member 7) and SLC22A17 (Solute Carrier Family 22 Member 17) were also in connection with cardiotoxicity among patients with osteosarcoma." (PMID 29970035, 2018).
hearing loss (1 paper, 2023). "Variants on the genes CRIP3, which plays a role in T-cell proliferation and metal-ion binding, and SLC22A7, have been found to be associated with hearing loss in humans." (PMID 38098998, 2023).
kidney cancer (1 paper, 2020). Primary or metastatic malignant neoplasm involving the kidney. "In kidney cancer, SLC22A6, SLC22A7, SLC22A13, SLC25A4, SLC34A1, and SLC44A4 were significantly downregulated." (PMID 32461965, 2020).
renal carcinoma (1 paper, 2016). A carcinoma arising from the epithelium of the renal parenchyma or the renal pelvis. "For example, MDM2, SLC16A3, LFT etc. show expression change in renal cancer; SLC22A7, ACHE, BMP4 etc. are associated with renal function." (PMID 27258182, 2016).
renal failure (1 paper, 2024). "Serum Mg2+ levels were associated with MUC1/TRIM46 (p = 2.9 × 10−7), SHROOM3 (p = 4.0 × 10−7), and SLC22A7 (p = 1.0 × 10−6) at nominal significance, which is in combination with the eQTL data suggesting that they are possible candidates for renal failure." (PMID 38279093, 2024).
tumor (13 papers, 2013 to 2024). "More recently, certain SLC22 family genes have been implicated as possible tumor suppressors, as in the cases of SLC22A7 in Hepatocellular Carcinoma and SLC22A1 in Cholangiocellular Carcinoma." (PMID 36230695, 2022). "As shown by the in vitro analyses, we also confirmed in vivo that tumor SLC22A7 level was lower in mice treated with miR-1229-3p mimics than in control mice treated with only atelocollagen." (PMID 32081926, 2020). "Five of those are found in comparisons of both tumor types: SLC22A6/OAT1, SLC22A7/OAT2, SLC22A8/OAT3, SLC22A12/URAT1, SLC22A13/ORCTL3." (PMID 36230695, 2022). "Interestingly, of the DE genes between tumor and normal kidney tissue (in bold), SLC22A6, SLC22A7, and SLC22A8 are OAT1, OAT2, and OAT3." (PMID 36230695, 2022). "However, such genes as IFI27 (−4.38), SLC22A7 (−3.97), IFIT1 (−3.91), TGFB3 (−3.71), and IFN-α induced (−3.72) also had stronger suppression at the transcript level in HCC-R tumor tissues." (PMID 24377043, 2013).
cancer (7 papers, 2020 to 2024). A tumor composed of atypical neoplastic, often pleomorphic cells that invade other tissues. "In this study, overexpression of miR-1229-3p induced the down-regulation of SLC22A7 in vitro and in vivo, so the suppression of 5-FU uptake into cancer cells would have occurred." (PMID 32081926, 2020). "SLC22A7 is reported to be a transporter of 5-FU in cancer cells." (PMID 32081926, 2020). "Six of these genes were not expressed or were very weakly expressed (ABCC11, SLC22A6, SLC22A7, SLC22A8, SLC22A9, SLCO1B1), and among the other eight genes, only gene ABCG2 showed significant difference in expression in cancer versus adjacent control tissue." (PMID 33917029, 2021). "Among the various cancers examined, SLC22A6, SLC22A7, SLC22A13, SLC25A4, and SLC34A1 were significantly downregulated, while SLC44A4 showed different expression patterns in different cancers (upregulated or downregulated)." (PMID 32461965, 2020). "We used the Oncomine database to analyze the expression levels of SLC22A6, SLC22A7, SLC22A13, SLC25A4, SLC34A1, and SLC44A4 in various cancers and their normal tissues." (PMID 32461965, 2020).
SLC22A7 also shares sentences with these, for which no sentence is quoted: colorectal cancer (3 papers); diabetes (3); chronic hepatitis C (2); lymphoma (2); autism spectrum disorder (1); cancers of the head and neck (1); cardiovascular disease (1); Cirrhosis (1); colon cancer (1); Diabetic nephropathy (1); Hypertension (1); kidney diseases (1); lung carcinoma (1); lymph node metastasis (1); ovarian carcinoma (1); pancreatic tumour (1); rectal cancer (1); schizophrenia (1); urinary bladder cancer (1).